CRP (C-reactive protein)
Diseases named in the same sentence as CRP in open-access papers (continued):
Sharing a sentence is not in itself a finding about the gene and the disease.
tumor (continued). "After adjusting for age, maximal tumor dimension, the presence of portal vein invasion, and the outcome of histology, a nonlinear relationship between the serum CRP levels and the risk of ER was observed." (PMID 25602444, 2015). "The mechanistic role of tumor-related CRP in HCC recurrence is largely unclear." (PMID 25602444, 2015). "Inflammation was evaluated by measuring C-reactive protein, a non-specific acute phase protein that serves as a surrogate for interleukin 6, an inflammatory cytokine associated with angiogenesis, tumour growth and metastases." (PMID 26157638, 2015). "The coordinated elevation of SAA and CRP in patients could be explained by the inflammatory response to tumor." (PMID 25884401, 2015). "In addition there is also evidence to support the use of CRP to help decide treatment response and identify tumor recurrence." (PMID 26717416, 2015). "On the basis of above clinical findings, some researchers hypothesized that high serum CRP levels may reflect the aggressiveness of the tumor or cytologic tumor spread." (PMID 25602444, 2015). "Concentrations of CRP were clearly elevated in patients with tumour metastases or recurrences." (PMID 26107255, 2015). "Inflammatory factors derive not only from the systemic reaction to malignancies, but also the secretion of tumor cells, including acute phase proteins like CRP, chemokines, cytokines like interleukin 6 (IL-6), transcription factor like NF-κB, circulating and infiltration immune cells and so on." (PMID 25934640, 2015). "Solely, an association between pre-treatment CRP serum levels and tumor size (p = 0.04) but no other clinic-pathologic parameter such as tumor stage (p = 0.16), or histological grade (p = 0.07), was observed." (PMID 26248232, 2015). "Furthermore, positive correlation regarding levels of Hs-CRP in serum and Child-Pugh class or tumor stage was also found, with significantly statistical difference (P = 0.006 and P = 0.002, respectively)." (PMID 26656354, 2015). "Moreover, serum soluble interleukin-2 receptor (sIL-2R), serum lactic dehydrogenase (LDH), and C-reactive protein (CRP) have been recently used as markers of tumor burden and disease activity in ML." (PMID 27408888, 2015). "Our study demonstrated that the CRP/Alb ratio was associated with some important clinicopathological characteristics in ESCC, including tumor size (P < 0.001), tumor differentiation (P = 0.019), T stage (P = 0.003), N stage (P = 0.015), M stage (P < 0.001) and TNM stage (P < 0.001)." (PMID 25934640, 2015). "Therefore, we also examined the association between these tumor markers (i.e., sIL-2R, LDH, and CRP) before and after treatment and disease recurrence." (PMID 27408888, 2015). "Furthermore, the combined effect of SCC-Ag and CRP on survival and their prognostic value were confirmed in a multivariate analysis after adjusting for age and recurrent tumor stage." (PMID 25061977, 2014). "Predictive factors of recurrence after nephrectomy in patients with RCC include anatomical (TNM classification), histological (pathological grade, histological vein invasion and tumor necrosis), clinical (symptoms and performance status) and biochemical (level of CRP) features." (PMID 24938498, 2014). "Furthermore, based on a CRP cut-off level of 2.0 mg/dl, mean tumor size reduction was significantly greater in patients with low CRP levels than in patients with high CRP levels in lesions with diameters < 20 mm (P = 0.002)." (PMID 24612599, 2014). "Moreover, the influence of both elevated SCC-Ag and CRP levels on overall survival (P<0.001, H.R. [95% CI]: 5.406 [2.210–13.222]) still existed after adjusting for the recurrent tumor stage and patient age." (PMID 25061977, 2014). "We show here by genotyping of 141 tumor/normal sample pairs that no recurrent mutations occur at the 3 CRP SNP sites, thus highlighting that the -286 mutations are highly specific to tumorigenesis." (PMID 25025473, 2014).
tumor (continued). "Patients with CCRCC with smaller lung metastatic lesions and lower CRP levels may achieve greater percent reductions in tumor size with sunitinib therapy than patients with extra-pulmonary lesions, large lung lesions, and/or higher CRP levels." (PMID 24612599, 2014). "CCRCC patients with lung metastatic lesions < 20 mm in diameter and lower CRP levels may achieve greater reductions in tumor size with sunitinib therapy than those with extra-pulmonary lesions, lung lesions ≥ 20 mm in diameter, and/or higher CRP levels." (PMID 24612599, 2014). "CRP is known as a sensitive but non-specific inflammatory marker produced by the liver which is associated with tumor progression in patients with HCC and is a useful biomarker for predicting outcomes after liver transplantation in patients with HCC." (PMID 24367506, 2013). "Several explanations have been proposed such as that CRP could directly impair immune functions allowing unrestrained tumour growth." (PMID 23497335, 2013). "Recently, in resected stage I-IIIA NSCLC patients we demonstrated densities of tumour-associated CD66+ neutrophils and CD163+ macrophages were correlated with adverse clinical prognostic factors as well as CRP and white blood cell (WBC) systemic inflammatory markers." (PMID 23945200, 2013). "It is likely that the association with muscle invasive disease among patients with high serum CRP levels may be due to tumor spread that cannot be detected either by routine imaging studies or by pathologic examinations." (PMID 23497335, 2013). "In addition, T-lymphocytes located at the periphery of tumors serve to increase the production of SCC-Ag, which causes accelerated tumor growth to be associated with elevated levels of SCC-Ag and CRP." (PMID 23383155, 2013). "It is of note that both CRP and NLR levels were significantly related to tumor burden and underlying hepatic reserve, known as the two key determinants of HCC survival, showing a linear positive relationship with tumor stages or Child-Pugh classes." (PMID 23409924, 2013). "In addition, patients who had preoperatively elevated CRP levels, should be closely monitored after hepatectomy because of a poor prognostic factor of tumor recurrence." (PMID 23618082, 2013). "For the serum CRP levels associated with HCC, high CRP was linked to the diffuse type of HCC and elevated preoperative CRP levels in patients with HCC associated with tumor size and portal vein invasion, and predicted recurrence after curative resection and a poor surgical outcome." (PMID 23618082, 2013). "On multivariate analysis of the prognostic factors for disease-free survival in HCC patients with malignant portal vein invasion, only the CRP level (hazard ratio, 1.133; 95% confidence interval, 1.028–1.249; P=0.012) was a significant independent predictor of tumor recurrence after liver resection." (PMID 23618082, 2013). "First, serum CRP levels may reflect the aggressiveness of the tumor, as they are the result of the immune response of the host to tumor growth." (PMID 24255664, 2013). "Moreover, elevated CRP-levels were found in 9.9, 25.4 and 64.8% of patients with G1, G2 and G3 tumours, respectively (p<0.001, Chi2 test)." (PMID 23497335, 2013). "We evaluated 1,161 RCC patients with complete patient and tumour specific characteristics as well as information about their pre-operative CRP-level, who had undergone either radical nephrectomy or nephron-sparing surgery at two German high-volume centres (University Hospitals of Hannover and Ulm)." (PMID 22958305, 2012). "Moreover, it is also possible that CRP is a part of the immune response of host which is studied as a consequence of tumor growth itself." (PMID 22912790, 2012). "Therefore, tumor status and aggressiveness can be directly reflected by the serum CRP levels of patients with AM-RCC." (PMID 22857740, 2012). "CRP and tumor markers were measured in serum or heparin-plasma as a routine analysis." (PMID 22963460, 2012).
tumor (continued). "We found that decreases in CRP during treatment correlated with tumour marker decreases." (PMID 22963460, 2012). "In the first carcinogenesis model, elevated CRP may be due to an inflammatory process in the local of cell line inoculation in addition to the tumor cell proliferation." (PMID 21811552, 2011). "First, tumour cell behavior: plasma CRP levels may reflect the aggressiveness of the tumour, that is, plasma CRP levels might sum up some prognostic information of well-known tumour characteristics, such as tumour stage and grade." (PMID 21639875, 2011). "The increase of white blood cell counts, in agreement with the elevated CRP levels, may be due to an inflammatory process and may have a role in the response against human malignant cells and the tumor remission after 14 days of cell line inoculation." (PMID 21811552, 2011). "Second, the response hypothesis: the immune response of the host as a consequence of tumor growth itself could be the reason for the elevation in CRP levels." (PMID 20673375, 2010). "Preoperative serum IL-6 and CRP levels might be markers of tumor invasion, LN metastasis, and TNM stage." (PMID 19457231, 2009). "Hypothetically, this may suggest that CRP may play a hole of a mucosal protective factor which deteriorates with tumour progression." (PMID 27956962, 2009). "Patients with DCD-expressing tumours did not have a significantly greater weight loss, lower BMI or higher CRP than those patients not expressing DCD (data not shown)." (PMID 18594538, 2008). "Study II assessed now, that the selected second transcription modulator, IFN-α besides pioglitazone, is complementary acting while tilting the systems biology of the tumor to a measurable response: Inflammation control in all patients with initially elevated CRP levels." (PMID 19690640, 2007). "A chronic inflammatory infiltrate remained an independent prognostic indicator on multivariate analysis when analysed with stage, age, sex, tumour grade, and serum CRP concentrations (P=0.013, hazard ratio 7.7 (1.5–38.0 95% CI); Cox's proportional hazards model)." (PMID 17088911, 2006). "Alternatively, C-reactive protein could directly impair immune function allowing unrestrained tumour growth and dissemination." (PMID 17024120, 2006). "Indeed, the systemic inflammatory response, as evidenced by elevated circulating concentrations of C-reactive protein, has been shown to be a disease-independent prognostic factor in a variety of tumours, when resections are carried out with curative intent." (PMID 16685271, 2006). "However, tumour tissue IL-1β protein levels were positively correlated with serum CRP concentrations (P=0.05, r=0.31; linear regression)." (PMID 17088911, 2006). "The tumour CD4+ T-lymphocytic infiltrate was directly associated with CD8+ (P<0.001) but not with C-reactive protein (P=0.556)." (PMID 17024120, 2006). "Alternatively, it may be that C-reactive protein plays a more pivotal role in the tumour–host relationship." (PMID 17024120, 2006). "Some authors hypothesised that soluble CRP prevents recognition and binding of tumour cells by IL-2-activated effector cells." (PMID 16940978, 2006). "We hypothesise that in this subgroup of MM patients with clinically relevant osteolytic lesions, a high tumour load can be assumed anyway, while the malignant potential is better indicated by CRP as surrogate marker for IL-6 levels." (PMID 16969356, 2006). "Indeed, the systemic inflammatory response, as evidenced by elevated circulating concentrations of C-reactive protein, has been shown to be a stage independent prognostic factor in a variety of operable tumours." (PMID 15726119, 2005). "Indeed, the systemic inflammatory response, as evidenced by elevated circulating concentrations of C-reactive protein, has been shown to be a disease-independent prognostic factor in a variety of operable tumours." (PMID 15597096, 2005).
tumor (continued). "C-reactive protein was associated with increasing age (P=0.016) and ER negative tumours (P=0.035) but not with size, type, grade or lymph node status." (PMID 15305191, 2004). "The reduction in cytochrome P450 3A function with acute-phase reaction was independent of the tumour type and C-reactive protein elevation was associated with poor performance status." (PMID 12177794, 2002). "As a pro-inflammatory factor, the level of cyr61 in ascites increases is associated with FIGO stage, initial tumor size > 10 cm, and residual tumor size, and may participate in the tumor metastasis and progression process by generating IL-6 and CRP in the OC inflammatory microenvironment." (PMID 41601649, 2026). "The association between baseline CRP elevation and inferior OS (HR = 3.337; p=0.044) underscores systemic inflammation’s role in ES-SCLC progression-a finding consistent with mechanisms linking interleukin-6-driven inflammation to immunosuppression and tumor aggressiveness." (PMID 41267986, 2025). "CRP, which is produced by hepatocytes in response to IL-6 stimulation, is a cost-effective and widely available marker of inflammation that may also contribute to an immunosuppressive tumour microenvironment by directly impairing T-cell function." (PMID 40091005, 2025). "However, other data suggests CRP has tumoricidal and anti-proliferative activities, highlighting a critical need to investigate the role of CRP in the tumor microenvironment (TME) so that its activities may be more advantageously regulated." (PMID 41614767, 2025). "In addition, CRP can suppress tumor lymphocyte activation and promote tumor immunosuppression." (PMID 40264786, 2025). "A multivariate analysis showed that mass forming tumor with mass larger than 5 cm and presence of metastasis at the time of PTBD served as a negative prognostic factor (p = 0.002), better survival was associated with lower preprocedural bilirubin and lower CRP (p = 0.003)." (PMID 39824949, 2025). "Also, diverse studies could be planned to assess salivary CRP diurnal variations, variations based on tumor staging and the post-treatment prediction of prognosis." (PMID 39851610, 2025). "Consequently, increased pre-treatment CRP may indicate both the present tumor load and the extent of the host’s systemic response that promotes disease development." (PMID 41283275, 2025). "Moreover, IL-15 and CX3CL1 plasma levels were positively correlated with markers of inflammation and high tumor burden (fibrinogen, lactate dehydrogenase, C-reactive protein, cell-free DNA, CXCL9) at pre-lymphodepletion, a biochemical makeup that has been associated with ICANS." (PMID 38833312, 2024). "Consequently, the reduction of tumor mass through systemic anti-tumor therapy could lead to diminished IL-6 production and subsequently to CRP normalization." (PMID 37695463, 2024). "In addition, many predictive biomarkers are based on immune cells or inflammatory cytokines, such as NLR, PLR, LMR, PD-1+ granulocyte percentage, SII, monocyte index, TGF-β, IL-6, and CRP, reflecting the clinical implication of tumor immune microenvironment in the efficacy of ICI therapy for HCC." (PMID 38169551, 2024). "Additionally, the hypothesis suggests that the presence of tumor cells, inducing tissue stress, can initiate an inflammatory response, serving as the stimulus for CRP synthesis." (PMID 38673838, 2024). "However, some patients with high CRP levels were found to have microsatellite-stable tumours." (PMID 39613865, 2024). "Importantly, inflammation in the tumor microenvironment may be reflected by circulating CRP levels and proteins related to early inflammation and have important effects." (PMID 38172843, 2024). "C-reactive protein (CRP), a key acute-phase reactant, independently predicts prognosis in many malignancies; its elevation accelerates angiogenesis through increased vascular growth factors and interleukins, thereby promoting tumor progression and decreased survival." (PMID 39877772, 2024).
tumor (continued). "After internalization, the intracellular concentrated ROS in tumor cells could trigger the instant transformation of the cationic CRP polymer to a neutral zwitterionic polymer for swift Cas9 and sgSTAT3 release, accompanied by Cas9 RNP reassembly to knock out the STAT3 gene in the genome." (PMID 38923275, 2024). "Additionally, CRP, when combined with albumin levels, erythrocyte sedimentation rate, neutrophil‐to‐lymphocyte ratios, and other factors, has been widely employed to predict tumor prognosis." (PMID 38923354, 2024). "However, some patients with an MSS tumour had a high CRP level." (PMID 39613865, 2024). "Consequently, CRP stands as a crucial biomarker for tumor prognosis and treatment responses." (PMID 39267838, 2024). "Thus, a combination of these two acute phase proteins, namely the C reactive protein-to-albumin ratio, may more accurately reflect the severity of inflammation, which is believed to be directly correlated with tumor progression." (PMID 39064483, 2024). "Inflammation-related cytokines, such as interleukin-6 (IL-6) and C-reactive protein (CRP), as well as changes in metabolism-related adipokines, such as adiponectin and leptin, have been shown to reflect a proinflammatory microenvironment that promotes tumor development and progression." (PMID 36670988, 2023). "In addition, we have proved, that simultaneous CXCL14 and CRP determinations might be more useful in CRC diagnosis than commonly used tumor marker – CEA, and CRP combination." (PMID 37848726, 2023). "For one, CRP has been described as an indicator of tumor burden and, as such, may act as a surrogate marker for growing and progressing tumors eliciting a stronger immunological response accompanied by CRP elevation." (PMID 37603206, 2023). "In addition, compared to the pTNM model, the model constructed based on PNI, CRP-to-albumin ratio, percentage of preoperative weight loss, CA19–9, pTNM stage and tumor location could more accurately predict patient OS (C-index = 0.714 vs. 0.630, P < 0.001)." (PMID 36386538, 2022). "CRP is a well-recognized hallmark of inflammation and has been shown to be an adequate inflammation-based and feasible prognostic marker for CRC, whereby increased plasma levels are associated with a worse prognosis for CRC, larger tumor size, higher recurrence rates, and decreased overall survival." (PMID 36361914, 2022). "Besides the classic marker CA125 as the most utilized laboratory marker in the diagnostic workup of suspicious adnexal masses, we also looked at CRP, as its production during carcinogenesis indicates tumor cell growth, an immune-mediated host-defense reaction against malignant cells, or both." (PMID 35804981, 2022). "Therefore, we considered that the detection method, gender, and tumor stage might be influential factors and a possible source of heterogeneity in CRP change." (PMID 35910071, 2022). "Therefore, patients presenting with increased serum levels of CRP might benefit from preoperative or follow-up PET imaging examinations to predict tumor progression and set individualized follow-up imaging intervals." (PMID 34882287, 2022). "Interestingly, the patients in our study showed a positive correlation between serum CRP levels and FC levels; this may reflect increased inflammatory activity at the tumor site." (PMID 35331198, 2022). "High lncRNA-ATB and miRNA-21 levels in circulating exosomes, together with high C-reactive protein levels and a large tumor size, are independent predictors of disease progression and mortality in patients with HCC; thus, these molecules may serve as prognostic biomarkers of HCC." (PMID 35185900, 2022). "Therefore, elevated CRP may not only be a response to progression of the tumor burden but also reflect tumor lysis and local tissue damage, which ultimately correlates with adverse survival outcomes." (PMID 36046647, 2022).